IL1B (interleukin 1 beta)
Diseases named in the same sentence as IL1B in open-access papers (continued):
Sharing a sentence is not in itself a finding about the gene and the disease.
thymic atrophy (1 paper, 2018). "While the exact mechanism by which the infiltrating granulocytes promote this thymic atrophy is unknown, RelB is known to repress Il1b and granulocyte extracellular traps could act as a platform for IL-1 activation." (PMID 29872433, 2018).
thymic lymphoma (1 paper, 2022). "In fact, we previously reported that certain cytokines such as IL-1β, IL-12p40 and IL-11 were secreted from macrophages after irradiation as assessed with a mouse model in which nearly 100% of mice develop thymic lymphoma after four-fractionated irradiation." (PMID 35336821, 2022).
thyroid nodule (1 paper, 2024). A small circumscribed mass in the THYROID GLAND that can be of neoplastic growth or non-neoplastic abnormality. "Transcriptomics suggested that the (IL-6, TNF-α, IL-1β)/JAK2/STAT3/VEGF pathway may be one of the key mechanisms in the treatment of thyroid nodules by JJJG." (PMID 39494342, 2024). "Meanwhile, this study is the first to explore and suggest that the (IL-6, TNF-α, IL-1β)/JAK2/STAT3/VEGF signaling pathway may be involved in regulating the development of thyroid nodules and is one of the possible therapeutic targets for JJJG." (PMID 39494342, 2024). "Key genes involved in thyroid nodules pathogenesis and JJJG treatment were revealed, such as Il6, Il1b, Jak2, Stat3 and Vegfa, etc.." (PMID 39494342, 2024). "This study indicates that JJJG efficiently ameliorates thyroid nodules by regulating the levels of FT3, FT4 and TSH in serum and suppressing (IL-6, TNF-α, IL-1β)/JAK2/STAT3/VEGF pathway in thyroid tissue, providing a potential therapeutic approach for thyroid nodules." (PMID 39494342, 2024). "Therefore, through transcriptomics in conjunction with literatures, we speculated that JJJG may treat thyroid nodules via (IL-6, TNF-α, IL-1β)/JAK2/STAT3/VEGF pathway." (PMID 39494342, 2024).
tonsil infection (1 paper, 2021). "The human tonsil infection model that we employed here has been previously shown to support productive HIV infection, cell death, and release of cytokines such as IL-1β and IL-10, which is similar to an HIV-induced inflammation in humans." (PMID 34446704, 2021).
trichotillomania (1 paper, 2017). A disorder characterized by repetitive pulling out of one's hair resulting in noticeable hair loss; the individual experiences a rising subjective sense of tension before pulling out the hair and a sense of gratification or relief when pulling out the hair. "Thus, the current findings may indicate common reduction of IL-1β across OCD and trichotillomania, but that trichotillomania is linked with a broader range of inflammatory changes." (PMID 29920483, 2017). "The current study examined a range of salivary inflammatory markers (IL-1β, IL-6, IL-8, and TNF-α) in a sample of patients with trichotillomania, and whether inflammation related to symptom severity and other clinical measures." (PMID 29920483, 2017).
Tricuspid regurgitation (1 paper, 2019). Failure of the tricuspid valve to close sufficiently upon contraction of the right ventricle, causing blood to regurgitate (flow backward) into the right atrium. "DLCO, KCO and tricuspid regurgitation (TR) velocity were significantly higher in patients with high serum IL‐1β." (PMID 30997045, 2019).
trypanosomiasis (1 paper, 2019). Infection with protozoa of the genus trypanosoma. "Indeed, in a model of T. brucei infection, treatment with antagonists of IL-1β and TNFα attenuated neurodegeneration, highlighting the significant role these pro-inflammatory cytokines play in trypanosomiasis-associated neuropathology." (PMID 31572363, 2019).
Tumor Lysis Syndrome (1 paper, 2021). a group of metabolic abnormalities that can occur as a complication during the treatment of cancer, most commonly after the treatment of lymphomas and leukemias. "Interestingly, Pt #17 showed low levels of IFNG, IL6, IL1B, C-reactive protein (CRP) and Ferritin, suggesting the grade 3 CRS might be attributed to tumor lysis syndrome or other inflammation pathways." (PMID 34518515, 2021).
type IV hypersensitivity reaction (1 paper, 2024). "Metal implants have the potential to trigger a type IV hypersensitivity reaction, where macrophage activation, induced by implant debris, leads to the release of interleukin (IL)-1b, the tumor necrosis factor, IL-6, and IL-8." (PMID 38592148, 2024).
Urethral stricture (1 paper, 2025). Narrowing of the urethra associated with inflammation or scar tissue. "In a rat urethral fibrosis model induced by TGF-β1, miR-146a-enriched exosomes derived from TNF-α-treated HUMSC suppressed urethral stricture by reduction of IL-1β/-6, IL-1 receptor-associated kinase 1 (IRAK1), TNF receptor-associated factor 6 (TRAF6), and NF-κB levels in target cells." (PMID 40676634, 2025).
urinary bladder transitional cell carcinoma (1 paper, 2017). "The differences between the two strains are also related to a different modulation in T24 (human urinary bladder transitional cell carcinoma) cells of inflammation mediators such as pro-inflammatory cytokines IL-6, IL-8 and IL-1β and the anti-inflammatory cytokine TGF-β." (PMID 28212280, 2017).
ventricular fibrillation (1 paper, 2025). A disorder characterized by an electrocardiographic finding of a rapid grossly irregular ventricular rhythm with marked variability in QRS cycle length, morphology, and amplitude. "Inflammatory cytokines (such as TNF-α, IL-6, IL-1β, IL-17) are involved in the pathogenesis of malignant VAs (ventricular tachycardia (VT) and ventricular fibrillation (VF)), but are largely overlooked in the management of heart rhythm disorders." (PMID 41574188, 2025).
vitamin A deficiency (1 paper, 2023). Deficiency of vitamin A due to malnutrition, malabsorption, or dietary lack. "In the mouse model of vitamin A deficiency, supplementation of β-carotene also downregulated the levels of intestinal inflammatory cytokines, TNFα, IL1-β, and IL-6, and immunomodulatory cytokines, IL22, IL23, and IL17." (PMID 37018237, 2023).
vitamin D (1 paper, 2014). "Upon A. fumigatus exposure, vitamin D deficiency led to enhanced and sustained expression of TNF-α, IL-1β, IL-6, CXCL1 and CCL3 both in vivo and in vitro." (PMID 24926881, 2014).
VRSA infection (1 paper, 2023). "In accordance, VRSA infection provoked upregulated relative mRNA expression levels of pro-inflammatory genes (IL-1β, TNF-α, and IL-6) and apoptosis-associated genes (caspase-3, caspase-9, and Bax)." (PMID 38282617, 2023).
X-linked agammaglobulinemia (1 paper, 2021). X-linked agammaglobulinemia (XLA) is a clinically variable form of isolated agammaglobulinemia, an inherited immunodeficiency disorder (see this term), and is characterized in affected males by recurrent bacterial infections during infancy. "Utilizing bone marrow-derived macrophages from BTK-deficient mice and PBMC from patients with X-linked agammaglobulinemia (XLA), this group found reduced IL-1β production and impaired inflammasome activation within mutant myeloid cells." (PMID 33818636, 2021).
Yersinia pseudotuberculosis infection (1 paper, 2022). "In the process of Yersinia pseudotuberculosis infection, GSDME and likely itself in neutrophils mostly contribute to IL-1β release." (PMID 36182937, 2022).
infection (4,846 papers, 1993 to 2026). The state of being infected such as from the introduction of a foreign agent such as serum, vaccine, antigenic substance or organism. "Knock-in mice that carry the human T300A variant exhibit perturbation of specialized IECs (i.e. Paneth cells and goblet cells), susceptibility to infection and IL1B (interleukin 1 beta) production." (PMID 41382985, 2026). "Patients have elevated levels of IL-6, IL-12, IL-1β, and other proinflammatory cytokines that contribute to infection clearance but at high levels cause severe, even fatal disease." (PMID 41400356, 2026). "The pro-inflammatory cytokine IL-1β exhibits contrasting effects during M. tuberculosis infection, with evidence indicating that it can protect the host and increase susceptibility to infection." (PMID 40005637, 2025). "Paralleling the impact of caspase-4 and caspase-5 on IL-1β release, during infection with M. kansasii, their absence was associated with a twofold reduction in cell death to baseline." (PMID 40272180, 2025). "Silencing of the gene encoding NLRP7 in human macrophages leads to a reduction in IL-1β and IL-18 release during infection with the bacterium S. aureus or L. monocytogenes, suggesting that NLRP7 activation mediates an inflammasome response." (PMID 41062723, 2025). "Danger signal-induced inflammasome activation drives caspase-1-mediated cytokine secretion (e.g., IL-1β/IL-18) and lytic cell death (pyroptosis), which are critical for host defense against pathogenic infections or tissue damage." (PMID 41208996, 2025). "IL-1β deficient mice were more likely to survive this infection compared to WT controls, however, this survival advantage was attenuated in 6-month-old mice." (PMID 40016339, 2025). "Auranofin administration increased the susceptibility of mice to infection with Mtb and impaired IL-1β and iNOS expression in pulmonary macrophages in vivo." (PMID 40602278, 2025). "The increases in IL-6 and IL-1β levels at 5 dpi are consistent with the high mortality rate associated with infection by the HY/HA-ΔL226/R229I strain." (PMID 40338080, 2025). "In turn, infection of trophoblast cells by C. trachomatis causes an increase in the concentration of interleukin-1β (IL-1β)." (PMID 40647668, 2025). "Mature GSDMD causes the pyroptosis of macrophages, releases mature IL-1β and IL-18, and triggers an inflammatory response to infection." (PMID 40933997, 2025). "In contrast, the AHI-24 group exhibited upregulation of inflammatory markers such as TNF-α and pro-IL-1β, reflecting general inflammation associated with recent infection." (PMID 41206241, 2025). "Gene expression of pro-inflammatory cytokines IL-1β, IL-2, IL-4, and IL-6, as well as IFNγ was significantly upregulated in nasal turbinates in response to infection with all VOCs, with the Gamma variant inducing the highest inflammatory response." (PMID 40295859, 2025). "IL-1β is associated with several immune reactions that include the recruitment of inflammatory cells to sites of infection and the production of genes that result in fever, hypotension, and vasodilation." (PMID 40331999, 2025). "The cps mutant did not display any loss of ability to induce inflammatory response upon infection and even triggered a higher level of IL-1β and TNF-α in macrophages." (PMID 39950808, 2025). "IL-1β is a potent pro-inflammatory cytokine, and crucial for host defense responses to infection and injury caused by microorganisms." (PMID 41294483, 2025). "Caspase activation was associated with the secretion of IL-1β, observed both 24 h and 7 days after infection." (PMID 41221328, 2025). "Both IL-1β and IL-6 are synergistic acute-phase cytokines that initiate systemic responses to infection and are associated with chronic inflammatory diseases." (PMID 41041334, 2025). "Despite this, 6-month-old IL-1β deficient mice showed significantly lower viral burden in the lungs at the peak of infection (3 dpi) compared to WT controls." (PMID 40016339, 2025).
infection (continued). "This dual action not only reduces infection risk but also supports wound healing, as further evidenced by the significant reduction in local inflammatory markers, such as IL-1β, observed in our in vivo studies." (PMID 40487154, 2025). "While S ΔmmpL4b infection induced high levels of secreted IL-1β from macrophages, the mutant resulted in significantly less IL-1β secretion, as determined by enzyme-linked immunosorbent assay and Western blotting." (PMID 39475242, 2024). "It has previously been reported that IL-1β blockade using a similar protocol in RSV mouse models can affect weight loss later in the course of infection." (PMID 39127259, 2024). "Our findings that (i) blocking antibodies abolished IsdB-mediated cytokine induction in human monocytes and (ii) human monocytes produced less IL-1β after infection with isdB-deficient live S. aureus than with isogenic WT bacteria lend support to this notion." (PMID 38112465, 2024). "The infection and corresponding tissue damage caused by DD elicit the host to produce elevated levels of pro-inflammatory cytokines, such as interleukin-1β (IL-1β) and interleukin-6 (IL-6), released into the blood stream." (PMID 39595313, 2024). "It should be noted that several studies have indicated IL-1β production as associated with the early stages of infection by Leishmania spp." (PMID 38707903, 2024). "They detected increased susceptibility of Aim2-/- mice to intratracheal infection, which they related to decreased caspase-1 cleavage as well as lower IL-1β and IL-18 levels in the lungs." (PMID 39324136, 2024). "One of the core changes induced by infection is an increase in neurotoxicity caused by inflammatory products (including IL-1β and TNF-α), oxidative stress (including lipid peroxidation), and apoptosis." (PMID 39240104, 2024). "The increase of infection related indexes, for example, serum levels of IL-1β, TNF-α, and IL-6, were significantly associated with a blood glucose rise." (PMID 38570745, 2024). "IL-6 is a pleotropic cytokine typically released in the context of infection and tissue damage induced by toll-like receptors (TLRs) and damage-associated molecular proteins (DAMPs), often in association with IL-1β and TNFα." (PMID 39595087, 2024). "Increased levels of IL-1β have been clinically associated with severe disease, and the data in the skin explant model suggest that IL-1β enhances infection right at the time of initial virus transmission in the skin." (PMID 38793609, 2024). "While CDT contributes to increased weight loss and cecal edema at 2 days post infection, the relative levels of inflammasome-associated cytokines, IL-1β and IL-18, in the cecum and distal colon are unchanged." (PMID 39298531, 2024). "Other results suggested that infection of human or murine phagocytes by L. major cause a parasite-mediated dysregulation of IL-1β on a transcriptional level." (PMID 38707903, 2024). "IL-1β is an important cytokine in both acute and chronic P. aeruginosa infection, where it has been associated with successful control of infection in acute settings, and deleterious pathology in chronic settings." (PMID 39015565, 2024). "IL-1RN is an antagonist of IL-1 that inhibits the activities of IL-1α and IL-1β and regulates several immunological and inflammatory reactions linked to IL-1, especially during the acute stage of infection and inflammation." (PMID 39354641, 2024). "As opposed to the polymorphisms in PTX3, the rs3024491 in IL-10 and rs2853550 in IL-1β were strongly associated with the infection status." (PMID 38790226, 2024). "Amygdalin also has anti-inflammatory effect, which can significantly reduce the increase of IL-1β and IL-6 inflammatory factors caused by infection." (PMID 39283878, 2024). "Collectively, these findings strongly suggest a relationship between the production of IL-1β at sites of infection, the local induction of PTX3, and the underlying genetic variability." (PMID 38790226, 2024).
infection (continued). "Among the several proinflammatory cytokines implicated during infection and immune challenges, IL-1β is quintessential as it is involved in acute and chronic inflammation." (PMID 38253695, 2024). "We investigated the mechanism underlying inflammasome-mediated interleukin (IL)-1β secretion during the PEDV infection of porcine intestinal epithelial (IPEC-J2) cells." (PMID 39728983, 2024). "IL-1β and IL-18 recruit macrophages and neutrophils in the site of infection, whilst mature GDSMD forms membrane pores that cause lytic cell death." (PMID 38256033, 2024). "Trophoblasts produce cytokines constitutively and in response to infection, including those associated with the inflammasome, such as IL-1β and IL-18, which control L. monocytogenes infection." (PMID 38771057, 2024). "In the large intestine, infection with the Alpha strain strongly correlated with IL-2, and Beta and Delta infections were highly associated with multiple inflammatory cytokines (IL-1β, IL-6, IL-8, IL-18, TGF-α and MIP-1α)." (PMID 38563680, 2024). "Innate cytokines TNFα and IL-1β also showed some association with prior exposure by natural infection, consistent with previous results, but elevation was more marginal and restricted to specific subgroups of pre-exposed individuals." (PMID 37885896, 2023). "G6PD-deficient individuals also produce lower levels of pro-inflammatory cytokines, IL-6, and IL-1β in peripheral mononuclear cells, and their granulocytes display diminished bactericidal activity and increased susceptibility to infection." (PMID 37753082, 2023). "IL1B encodes the cytokine IL‐1β, which is produced by monocytes in response to infection and is closely related to the innate immune response and immune regulation." (PMID 37078407, 2023). "The genes encoding for markers of inflammation, namely Tnf, Il1b, Il6, Il23a, and Cxcl10 were induced with infection in Tln1fl/fl mice and significantly decreased in the colon tissues from infected Tln1Δmye mice compared to infected Tln1fl/fl mice." (PMID 38102166, 2023). "Increased IL-1B is also a key mediator in immune response to infection and injury, and associated with autoinflammatory diseases." (PMID 37965360, 2023). "Pro-inflammatory cytokines, such as IL-1β and IL-6, can mediate host inflammatory processes and produce a rapid immune response after infection with pathogenic microorganisms." (PMID 37835612, 2023). "Consistent with previous reports, bodyweight loss in unvaccinated animals after H7N7 infection was also associated with elevated IL-1β levels, whereas IL-1β levels were lower in the young vaccinated animals that exhibited less bodyweight loss." (PMID 37063291, 2023). "IL-1β has been linked to many immune reactions, including the recruitment of inflammatory cells to the site of infection." (PMID 37953818, 2023). "IL-1β is a strong stimulator of immune and inflammatory responses that cause immune cell recruitment and activation at sites of inflammation or infection." (PMID 37175425, 2023). "Depending on the pathogen, knockout mice are either more or less susceptible to infection compared to control animals, and IL-1β release is rather delayed than inhibited." (PMID 37771587, 2023). "Other studies have shown that IL1B-511 T allele carriers exhibit an overexpression of IL-1β in the antrum and fundus of Japanese and German patients following infection by H. pylori." (PMID 36838318, 2023). "Upon infection, S. aureus induces the expression of genes encoding pro-inflammatory cytokines, including IL-6, IL-1β, and TNF-α." (PMID 37759998, 2023). "IL1B has been recognized as a marker for cellular stress, contributing not only to anti-infection activities but also to various inflammatory-associated disorders and acute tissue damage." (PMID 38077419, 2023). "The expression of IL-32 is upregulated by several cytokines, including TNF and IL-1β, as well as by infection, pathogen-associated molecular patterns (PAMPs) and oxidative stress." (PMID 37686029, 2023).